RPS25 (ribosomal protein S25)
Description:
Component of the small ribosomal subunit. The ribosome is a large ribonucleoprotein complex responsible for the synthesis of proteins in the cell.
Synonyms: S25; eS25
Tractability: Small molecule: an approved drug acts on it; a structure with a bound ligand is known; a high-quality ligand is known. PROTAC: ubiquitination databases record sites on it; its protein half-life has been measured; a small molecule that binds it is known. Other modalities: a drug acting on it is in phase 2 or 3 trials.
Target class: Other cytosolic protein
Gene: Protein-coding gene on chromosome 11 (119,015,508 to 119,018,724, reverse strand). Ensembl gene ENSG00000118181.
Subcellular location: Cytoplasm
Subcellular location (Human Protein Atlas): Cytosol; Endoplasmic reticulum; Nucleoli
Pathways (Reactome):
Metabolism of proteins: Eukaryotic Translation Termination; Formation of a pool of free 40S subunits; Formation of the ternary complex, and subsequently, the 43S complex; GTP hydrolysis and joining of the 60S ribosomal subunit; L13a-mediated translational silencing of Ceruloplasmin expression; PELO:HBS1L and ABCE1 dissociate a ribosome on a non-stop mRNA; Peptide chain elongation; Ribosomal scanning and start codon recognition; SRP-dependent cotranslational protein targeting to membrane; Translation initiation complex formation; ZNF598 and the Ribosome-associated Quality Trigger (RQT) complex dissociate a ribosome stalled on a no-go mRNA
Disease: SARS-CoV-1 modulates host translation machinery; SARS-CoV-2 modulates host translation machinery; Viral mRNA Translation
Metabolism of RNA: Major pathway of rRNA processing in the nucleolus and cytosol; Nonsense Mediated Decay (NMD) enhanced by the Exon Junction Complex (EJC); Nonsense Mediated Decay (NMD) independent of the Exon Junction Complex (EJC)
Cellular responses to stimuli: Response of EIF2AK4 (GCN2) to amino acid deficiency
Developmental Biology: Regulation of expression of SLITs and ROBOs
Metabolism: Selenocysteine synthesis
Gene Ontology:
Molecular function: protein binding; RNA binding; structural constituent of ribosome
Biological process: ribosomal small subunit biogenesis; rRNA processing; cytoplasmic translation; translation
Cellular component: cytoplasm; cytosol; cytosolic ribosome; cytosolic small ribosomal subunit; endoplasmic reticulum; extracellular exosome; nucleolus; nucleus; postsynaptic density; ribosome; small ribosomal subunit; nucleoplasm; synapse
Genetic constraint (gnomAD): Loss-of-function variants: 1 observed, 12.35 expected, observed/expected ratio (o/e) 0.081, 90% interval 0.028 to 0.38. The upper end of that interval is the gene's LOEUF score, 0.38, which puts it in group 1 of 6, group 1 being the genes least tolerant of losing a copy. Missense variants: 50 observed, 113.75 expected, observed/expected ratio (o/e) 0.44, 90% interval 0.35 to 0.56. Synonymous variants: 45 observed, 42.95 expected, observed/expected ratio (o/e) 1.05, 90% interval 0.82 to 1.34.
Homologues: Orthologues: pig RPS25 (100% identical), rat Rps25l3 (98% identical), tropical clawed frog rps25 (96% identical), zebrafish rps25 (90% identical), Drosophila melanogaster RpS25 (67% identical), Caenorhabditis elegans rps-25 (61% identical).
Diseases named in the same sentence as RPS25 in open-access papers:
RPS25 is named in the same sentence as 27 diseases in open-access papers, as found by Europe PMC text mining. Sharing a sentence is not in itself a finding about the gene and the disease. The quoted sentences say what the papers report.
leukemia (2 papers, 2022 to 2023). A malignant (clonal) hematologic disorder, involving hematopoietic stem cells and characterized by the presence of primitive or atypical myeloid or lymphoid cells in the bone marrow and the blood. "The RPS25 gene was demonstrated to be overexpressed in human leukemia cells which exhibit chemotherapy resistance to adriamycin." (PMID 36831382, 2023). "There were many leukemia-related genes in the up-regulated genes of K1 group, such as UBB (P=1.56e-50), MIF (P=2.76e-50), DRAP1 (P=1.72e-49), RPS25 (P=1.9e-49), EIF3K (P=4.77e-49), SSNA1 (P=1.27e-48), GPX4 (P=3.01e-48), PHB2 (P=7.13e-48), NME2 (P=2.44e-47) or CFL1 (P=4.07e-47)." (PMID 36408189, 2022).
adult T-cell leukemia (1 paper, 2021). "RPS25 was shown to be a potential biomarker of lung adenocarcinoma and adult T-cell leukemia, while CEP57 was associated with prostate cancer." (PMID 34208938, 2021).
breast carcinoma (1 paper, 2017). "Totally 15 breast cancer risks genes were obtained (Benjamini & Hochberg FDR < 0.05) and 6 of them (FAM84B, AAGAB, RPS25, SH3BP4, KRT80, TANK) showed the most significant correlation with the patient survival." (PMID 28621677, 2017).
Fusarium infection (1 paper, 2024). "The increase in protein expression revealed that the expression of RPS25 in Vanilla planifolia Jacks is an early plant response to Fusarium infection." (PMID 39336771, 2024).
Huntington disease (1 paper, 2023). Huntington disease (HD) is a rare neurodegenerative disorder of the central nervous system characterized by unwanted choreatic movements, behavioral and psychiatric disturbances and dementia. "RPS25 participates in nucleotide repeat expansions through the regulation of an unconventional translation process that is commonly associated with the pathogenesis of Huntington’s disease." (PMID 37761892, 2023).
multiple myeloma (1 paper, 2019). "Finally, RPS25 binds to c-Myc mRNA IRES and stimulates its activity during endoplasmic reticulum stress in multiple myeloma cells." (PMID 31296583, 2019).
myelodysplastic syndrome (1 paper, 2018). A clonal hematopoietic disorder characterized by dysplasia and ineffective hematopoiesis in one or more of the hematopoietic cell lines. "The co-overexpression RPS25 and RPS4X detected in one cluster of AML has been previously identified as contributing to the poor risk signature in myelodysplastic syndrome." (PMID 29530001, 2018).
neuroblastoma (1 paper, 2025). Neuroblastoma (NB) is the most common solid, extracranial childhood tumor. "(D) A western blot analysis of FMR99xG normalized to Vinculin from the human neuroblastoma cell line (SH-SY5Y) upon silencing of either RPS26 or RPS25." (PMID 40377206, 2025).
neuropathic pain (1 paper, 2017). Chronic pain caused by damage to nerve fibers. "The E3 ubiquitin ligase Nedd4 is decreased in DRGs of SNI mice, and ribosomal protein Rps25, as well as other ribosomal proteins are downregulated in a model for HIV-associated neuropathic pain." (PMID 29422837, 2017).
renal carcinoma (1 paper, 2021). A carcinoma arising from the epithelium of the renal parenchyma or the renal pelvis. "Most of the genes have usually been investigated as prognostic biomarkers in renal cancer, and RPS18, RPL30, NME2, and RPS25 usually have been investigated as unfavorable predictors, while GAB2 has been reported as favorable predictor in renal cancer." (PMID 34208938, 2021).
schizoaffective disorder (1 paper, 2019). "Genes with the least variable localization included components of the ubiquinol-cytochrome c reductase complex (Uqcrq, Uqcr11), ATP synthase complex (Atp5e, Atp5k), and ribosomal subunits (Rplp0, Rps25), some of which in humans have been implicated in schizophrenia and schizoaffective disorder." (PMID 30678683, 2019).
Shwachman-Bodian-Diamond Syndrome (1 paper, 2023). "In particular, MCM2 (minichromosome maintenance complex 2), MCM5, MCM7, multiple copies in T-cell lymphoma-1, RPS25 ribosomal protein S25, and Shwachman-Bodian-Diamond Syndrome were successfully confirmed." (PMID 37391046, 2023).
tumor (5 papers, 2018 to 2024). "It was worth mentioning that five of them were downregulated in tumor samples, including DLAT, MTF1, PDZD4, FDX1, and RPS25, and the rest of the genes were all upregulated." (PMID 36010978, 2022). "RPL30, RPL31, RPS25, and FAU positively correlated with tumor-infiltrating lymphocytes (TIL) and macrophages." (PMID 34760386, 2021). "RPS6, RPS19 and RPS25 helps in the transcription initiation of viral genes while RPL5 and RPL11 acts as tumor suppressors by degrading the mRNA of c-myc, through RNA induced silencing complex (RISC)." (PMID 29568375, 2018).
neurodegenerative disease (3 papers, 2020 to 2022). A disorder of the central nervous system characterized by gradual and progressive loss of neural tissue and neurologic function. "In contrast, one study confirmed that RPS25 is a therapeutic target for neurodegenerative diseases caused by nucleotide repeat amplification, which indirectly confirms the role of RPS25 in the pathophysiological process of AD." (PMID 36072674, 2022). "It has been suggested that RPS25 might be a potential therapeutic target for C9orf72-related neurodegenerative diseases caused by nucleotide repeat expansions, which could support our findings indirectly." (PMID 34225819, 2021). "Given the many alterations of the RPS25 knockout that cannot be rescued and the suggestion that eS25 is required for efficient repeat-associated non-AUG (RAN) translation that occurs in neurodegenerative diseases, we asked whether such a phenotype can be rescued." (PMID 32463448, 2020).
infection (1 paper, 2020). The state of being infected such as from the introduction of a foreign agent such as serum, vaccine, antigenic substance or organism. "We therefore performed a time-course infection experiment with DENV-luc and WT, RPS25 KO, and addback cells." (PMID 32463448, 2020). "Finally, performing DENV-luc infections on additional cell lines for multiple durations, we found that the protection against DENV-luc in both RPS25 knockouts was clear and significant across the first 72 hours of infection, and the eS25-HA addback consistently failed to rescue sensitivity." (PMID 32463448, 2020). "To understand the nature of flavivirus resistance at late stages of infection, we imaged DENV-infected WT and RPS25 KO cells stained for structural (envelope, E) and non-structural (NS3) proteins." (PMID 32463448, 2020). "While a strong reduction of luciferase was observed at 24 hours post-infection for the RPS25 KOs, we observed only minor differences between cell lines at 4- and 8-h post-infection, indicating that eS25 is not required for viral entry or initial translation." (PMID 32463448, 2020).
RPS25 also shares sentences with these, for which no sentence is quoted: adenocarcinoma (1 paper); amyotrophic lateral sclerosis (1); escherichia coli infection (1); lung adenocarcinoma (1); malaria (1); mental disorder (1); parathyroid adenoma (1); prostate carcinoma (1); Salmonella Infections (1); schizophrenia (1); tauopathy (1); viral infection (1).